MIR6791 (microRNA 6791)
Synonyms: hsa-mir-6791
Gene: MicroRNA gene on chromosome 19 (6,736,712 to 6,736,778, reverse strand). Ensembl gene ENSG00000283950.
Homologues: Orthologues: chimpanzee MIR6791 (100% identical).